OR6P1 (olfactory receptor family 6 subfamily P member 1)
Description:
Odorant receptor.
Tractability: Antibody: its Gene Ontology location is reachable by antibodies, with high confidence; UniProt places it where antibodies can reach, with medium confidence; UniProt predicts a signal peptide or a membrane-spanning region.
Gene: Protein-coding gene on chromosome 1 (158,560,606 to 158,570,580, reverse strand). Ensembl gene ENSG00000186440.
Subcellular location: Cell membrane
Subcellular location (Human Protein Atlas): Mid piece; Principal piece
Pathways (Reactome):
Sensory Perception: Expression and translocation of olfactory receptors; Olfactory Signaling Pathway
Gene Ontology:
Molecular function: olfactory receptor activity; G protein-coupled receptor activity
Biological process: detection of chemical stimulus involved in sensory perception of smell; G protein-coupled receptor signaling pathway
Cellular component: plasma membrane; membrane
Genetic constraint (gnomAD): Loss-of-function variants: 13 observed, 11.64 expected, observed/expected ratio (o/e) 1.12, 90% interval 0.73 to 1.72. The upper end of that interval is the gene's LOEUF score, 1.72, which puts it in group 6 of 6, group 1 being the genes least tolerant of losing a copy. Missense variants: 451 observed, 370.97 expected, observed/expected ratio (o/e) 1.22, 90% interval 1.12 to 1.31. Synonymous variants: 177 observed, 147.99 expected, observed/expected ratio (o/e) 1.2, 90% interval 1.06 to 1.36.
Homologues: Orthologues: chimpanzee OR6P1 (99% identical), macaque OR6P1 (95% identical), dog OR6P1 (90% identical), pig OR6P1 (89% identical), rabbit OR6P1 (88% identical), guinea pig OR6P1 (87% identical). Paralogues in human: OR6B3 (53% identical), OR6B2 (52% identical), OR11L1 (45% identical), OR6Q1 (45% identical), OR9G4 (44% identical), OR5A1 (43% identical), OR8I2 (43% identical), OR5A2 (42% identical), OR8A1 (42% identical), OR8B4 (42% identical), OR8D1 (42% identical), OR5B12 (42% identical), and 84 more.